CD4 (CD4 molecule)
Diseases named in the same sentence as CD4 in open-access papers (continued):
Sharing a sentence is not in itself a finding about the gene and the disease.
infection (continued). "Our data indicate that HVEM contributes to HSK immunopathology by upregulating activation and expansion of the CD4+ T cells that secrete IFN-γ following infection." (PMID 32398314, 2020). "All nine animals infected with the parental SIVmac239 construct or showing rapid reversion after infection with the CD3ko-Nef derivative showed only transient CD4+ T cell responses against SIV AT-2 during the early phase of infection." (PMID 32075764, 2020). "In infected T-bet−/− mice, the induction of TNF-α was maintained in CD4+ T cells, whereas infection resulted in enhanced Th17 responses, which were largely undetectable in infected WT mice." (PMID 32591391, 2020). "The interaction of human immunodeficiency virus with human cells is responsible for all stages of the viral life cycle, from the infection of CD4+ cells to reverse transcription, integration, and the assembly of new viral particles." (PMID 32625189, 2020). "Accordingly, L. major-infected mice upregulated PD-1 on activated CD4+ T effector cells and PD-L1 on resident macrophages and infiltrating monocytes at the site of infection." (PMID 33193363, 2020). "Increasing evidence shows that CD103 is induced by infection or inflammation in both tissue resident CD4+ and CD8+ T cells." (PMID 32974219, 2020). "We also did not observe differences in the magnitude of the endogenous anti-viral CD8+ or CD4+ effector T cell response in the presence of infection-experienced compared to naive Tregs." (PMID 32433493, 2020). "It was found that if during or prior to vaccination mice had their CD4+ T cell compartment depleted using antibodies, then the protective effect of vaccination was abrogated and mice succumbed to infection with MA-EBOV." (PMID 33679690, 2020). "In this context, non-infected XCR1+ (CD8α+) DCs were critical and responsible for the initial activation of naive CD8+ T cells by cross-priming at later time points of infection and were supported by previously primed CD4+ T cells." (PMID 32765505, 2020). "The CTL memory generation depends on CD4+ T-cell help, and infection of CD4+ T cells results in impaired T-cell help." (PMID 33101401, 2020). "At different time points of infection, single lung cell suspensions were prepared, and intracellular staining of IFNγ in CD4+ T cells was performed after 4 hrs of incubation in medium or after restimulation with anti-CD3/CD28." (PMID 33375150, 2020). "To this end, we infected CD4+ T cells from HIV-uninfected subjects using different models of infection, and then co-cultured with autologous CD8+ T cells." (PMID 32941545, 2020). "When compared with the levels of before infection, more IL-2+ CD4+ T cells and IL-2+ CD4+ TCM cells were elicited in the spleen and the lung of the CMFO/DMT group after infection with M. tuberculosis." (PMID 32953889, 2020). "The association factors included high zenith VL, low nadir CD4 + T cell counts, long term ART, Manchu, and subtype B′ infection." (PMID 32066392, 2020). "Combined, these data reveal that, in the primary CD4 T cell response to Lm-2W1S infection, the number of Th1 effector CD4 T cells was reduced in the absence of CD30 and OX40, reflecting the early loss of cytokine-producing Th1 effector cells." (PMID 32647184, 2020). "Four weeks after infection, CD4+ T cells were isolated from infected mice or naive OT-IItransgenic mice, stained with carboxyfluorescein succinimidyl ester, and transferred to recipient mice (CD45.1) that had been infected with PR8 6 days previously." (PMID 33251497, 2020). "Whereas HIV-infected CD4+ T cells die within a few days of infection, in vitro studies suggest that macrophages are resistant to the cytopathic effects of HIV replication." (PMID 32971935, 2020). "The number of CD4+CD25+FoxP3+ Tregs was lower in Cse−/− mice lungs at 2 weeks post-infection compared to WT, which was reversed after 4 weeks of infection, suggesting that Cse−/− mice can better control pro-inflammatory immune responses at later time points." (PMID 33330130, 2020).
infection (continued). "There is growing evidence that TRM (e.g., CD4+TRM) cells play a crucial role in protective immunity following natural infection and their subsequent secondary exposure." (PMID 32098623, 2020). "The further survival analysis demonstrated that the triple infection group exhibited faster CD4+ T-cell decline." (PMID 32038599, 2020). "The LR is stable over long periods in therapy suppressed individuals; the result of infection in naturally long-lived memory CD4 T cells that are continually replenished by clonal expansion and homeostatic proliferation." (PMID 32318356, 2020). "Identification of key regulators in HIV-1 trans-infection between DC and CD4+ T cells has the potential for the development of targeted therapy to reduce trans-infection of HIV-1 in vivo." (PMID 32075937, 2020). "To visualize the CD4 T cells in situ in the GT late after infection (day 50 post infection) we performed an immunohistochemical analysis." (PMID 31993218, 2020). "In such mice, IFN-γ production is reduced in CD4+ T cells, yet mice are able to control infection similarly to wild-type (WT) animals at the early stages of infection but ultimately lack the capacity to control it, succumbing weeks after challenge." (PMID 32591391, 2020). "The infection process is initiated with the binding of viral glycoprotein to host receptor CD4 with the sequential docking of the chemokine coreceptor CCR5 or CXCR4." (PMID 32858917, 2020). "CD4 T cells in the brain produce IL-21 during early infection by the gliatropic JHMV coronavirus and CD8 T cells upregulate the IL-21 receptor (IL21R); notably, IL21R−/− CD8 T cells have impaired granzyme B and IFNγ production." (PMID 32971931, 2020). "Spleens and MLNs were harvested at 10, 50 and 100 days post infection and Salmonella-specific CD4+ T cell responses were quantified using the 2W1S-MHC Class II tetramer and magnetic bead enrichment prior to flow cytometry analysis as we have done previously." (PMID 32722409, 2020). "Specifically, the number of 2W1S-specific CD4 T cells in the sham-treated mice expanded 44-fold during the 7 days after secondary infection, but only 6-fold in the CLP-treated mice." (PMID 32903436, 2020). "We observed a trend towards increased frequencies of PD1 expressing central memory CD4+ T cells during acute infection (p = 0.5) suggesting early exhaustion that was reversible after the acute infection stage." (PMID 32886726, 2020). "The percentages of CD3+ T cells, B cells, CD4+ T cells, Treg cells, and Th17 cells were elevated in the infection groups compared to the control animals." (PMID 32085808, 2020). "Average CD4+ T cell counts were lower among transplant recipients with infection while CD4:CD8 T cell ratios (average ratio 1.02) were similar among uncomplicated and infected liver transplant recipients." (PMID 33072022, 2020). "Consistent with the results obtained for Batf3−/− infection with the avirulent strain RHΔku80Δrop5, depletion of CD4 T cells before challenge with RHΔku80 significantly affected survival of Batf3−/− mice." (PMID 32669460, 2020). "CD8+ T-cells, along with CD4+ Th1 cells, are involved in the clearance of primary infection through IFN-γ production, which boosts the leishmanicidal capacity of macrophages via nitric oxide (NO) production." (PMID 32630347, 2020). "After propensity-score-matching, our data indicated that IFN-γ+CD4+ T cell number impacted the prognosis of CRO infection independently." (PMID 33072617, 2020). "Recently, it was shown that infection of human DCs with different MTB-strains varied in their potency of activating an effective CD4+ cell response since less virulent strains triggered a strong CD4+ cell activation that contained the infection." (PMID 32033104, 2020). "The development of these CD4+ T cell subsets was mediated by COX-2/PEG2 signaling upon DC infection." (PMID 32023904, 2020). "• Infection promotes the IL-27 expression by splenic CD8α+ and CD4+ DC at days 1, 14, and 28 post-infection." (PMID 32849534, 2020).
infection (continued). "Like in blood, HIV preferentially targets memory CD4+ T cells in the endometrium, but these cells exhibit unique phenotypes and sustain much higher levels of infection." (PMID 32452381, 2020). "We show that ADP-ribosylation factor 1 (ARF1), bridging integrator 1 (BIN1), and Rab GTPases RAB7L1 and RAB8A are important regulators of HIV-1 trafficking to the VS and therefore the infection of CD4+ T cells." (PMID 32075937, 2020). "Results from controlled human infection studies have shown that regulatory CD4+ T cells (Tregs) are important in suppressing effector T cells." (PMID 33604308, 2020). "Latent infection was also significantly higher in CD4+ T cells cultured with mDCs compared to pDCs (mean number of latently infected cells 37 and 1 EGFP+ cells/104 cells, respectively, p = 0.0019)." (PMID 32109259, 2020). "Research into the role of the CD4 + T cells as controllers of infection in the fetal mouse brain found that CD4 + T cells suppress the reactivation of MCMV in latently infected newborn mice." (PMID 33096622, 2020). "HIV-1 protein Env has been proposed to downregulate autophagy by activating mTOR and reducing lysosomal enzyme activity in DCs, thereby inhibiting antigen presentation and enhancing the transfer of infection into CD4+ T cells." (PMID 32265919, 2020). "We used a miRNA microarray to assess miRNA expression in CD4+ T cells of rEg.P29 vaccination of echinococcus granulosus secondary murine infection model, where bioinformatics analysis revealed that miR-374b-5p was significantly differentially increased." (PMID 32908913, 2020). "Although the human genome comprises hundreds of thousands of endogenous retroviral repeats, we found that infection of primary CD4+ T cells with HIV-1 primarily increases the transcription of ERV9 family members, including LTR12C solo-LTRs." (PMID 33021676, 2020). "Against infections with flaviviruses, CD4+ T cells play an important role as was demonstrated e.g., for WNV and ZIKV." (PMID 32806696, 2020). "To address this limitation, we performed redirected T cell cytotoxicity assays using CBMC as a source of neonatal CD8+ T cells for use as effectors, and autologous cord blood CD4+ T cells for use as targets after infection with HIV-1 in vitro." (PMID 32373131, 2020). "In our experimental model of thymectomy during infection, we observed potential decreases in cytokine production capacity by CD4+ T cells in thymectomized animals, which mirrors the diminished functional capacity of naïve T cells seen with aging in humans." (PMID 32722409, 2020). "After four cycles (day 12), infection rates increased to >4% in the presence of 17.5 μg/mL CD4-Ig (IC80) for all replicates, which was set as a threshold to indicate viral escape." (PMID 32690692, 2020). "Total numbers of 2W1S-specific CD4 T cells in the spleen were determined before and after the second Lm-2W1S infection." (PMID 32903436, 2020). "There was an increase in both the percentage and number of CD4+ T cells expressing Tbet in the mice that were given Moringa before infection." (PMID 32033605, 2020). "Here, we sought to compare the differences between memory and naïve antigen-specific CD4+ T cells in the same mouse following secondary infection using transgenic CD4+ T cells (NR1 T cells)." (PMID 33091023, 2020). "Although CD4 T cell help is dispensable for short-term acute LCMV infection, LCMV-specific CD4 T cells will get activated during acute LCMV WE infection and provide T cell help." (PMID 32991634, 2020). "Many immunoregulatory molecules and pathways, most notably those associated with interleukin-10 (IL-10) production, are activated following infection, which can suppress antiparasitic CD4+ T cell functions." (PMID 32908913, 2020). "Between 30 and 90 days after infection, these reactive CD4+ T cells acquire expression of CD69 and CD103, the retention markers, and reside in the papillary dermis." (PMID 33633737, 2020).
infection (continued). "During TFH differentiation, EZH2 expression spikes within 2 days after infection and then decreases to the baseline level that is comparable to naive CD4+ T cells." (PMID 30842630, 2020). "Early after infection, CD4 T cells were Th1 polarized, switching thereafter to an IL-10 dominated profile consistent with observations in humans and rodents." (PMID 33604562, 2020). "iPSC-MG and MMG were readily infected with R5-tropic HIV, while C20 and HMC3 lack CD4 and require pseudotyping for infection." (PMID 33213476, 2020). "Findings from humans and experimental animal model have demonstrated that CD4+T cells, especially Th1 type of response are the crucial component in mediating protective immunity in both primary and secondary infections with Chlamydia." (PMID 32626664, 2020). "Mice pre-infected with CnH99 for 2 weeks before CD4+ T cell transfer had significantly greater survival compared to mice with pre-infection period of 3 or 4 weeks." (PMID 33133067, 2020). "After 3, 6, 9 and 12 months post-infection, mice (including the homochronous control mice) were respectively sacrificed to determine differential expression of CD3ζ in CD4+ and CD8+ T cells from spleens." (PMID 32029006, 2020). "HA bound to virion-incorporated CD44 interacts with CD44 on the surface of FRCs and thereby promotes virus binding to FRCs (virus capture) and subsequent trans-infection of CD4+ T cells." (PMID 32752131, 2020). "Infection assays in CD4+ T cells revealed that TM and EM cells were most frequently infected by all pseudoviruses (46% and 25% of total infected cells respectively) compared to other subsets." (PMID 32762760, 2020). "We first set out to generate a cell-to-cell transmission model to induce HIV-1 endocytosis in human CD4+ T cells and to follow intracellular trafficking of the virus when viral membrane fusion is blocked, preventing the establishment of productive infection." (PMID 31919342, 2020). "Experimental pulmonary infection of A/J mice with strain LW10 results in enhanced IL-17 and gamma interferon (IFN-γ) production by CD4+ T cells that decreases as the infection is resolved." (PMID 31911495, 2020). "There is impaired protection against infection by pulmonary F. tularensis LVS in CD4+CD8+-depleted MR1−/− mice in contrast to their wild-type counterpart, which demonstrates MAIT cells' significance in mucosal immunity in absence of CD4+ and CD8+ T cells." (PMID 32536923, 2020). "Priming of infants with an aP vaccine induces mixed polarized CD4+ T-cell immunity which is Th2 skewed, while wP primed CD4+ T-cell immunity in animal models is Th1/Th17 polarized which is comparable to what is found after natural infection." (PMID 32429152, 2020). "In several infection models, IL-21 has been identified as the CD4 T help needed for formation and survival of TRM and TEX." (PMID 32971931, 2020). "Average CD4:CD8 T cell ratios decreased from 1.64 pre-SIVmac239 infection to 1.14 in acute infection, and to 0.81 in chronic infection." (PMID 32922404, 2020). "This life-long latent reservoir is quickly established in vivo after infection and consists mainly of memory resting (r)CD4 T cells harboring the viral genome integrated into their DNA5,6." (PMID 33339855, 2020). "After cycles 5 and 6 (days 15 and 18), infection rates also increased in the presence of 22.5 μg/mL CD4-Ig (IC95), and viral escape was observed for two of three replicates." (PMID 32690692, 2020). "Specifically, one patient from group 1 and one from group 2 developed strong CD4 T cell responses, but nevertheless had an early virus rebound and prolonged infection." (PMID 33262993, 2020). "High levels of FoxP3+CD4+ T cells are present in the CNS of virus-infected mice as early as 3 d after infection." (PMID 33086489, 2020). "It was also found that when HIV-1 Env binds to DC-SIGN it triggers trans-infection of CD4+ T cells, deregulation of DC function, prevention of DC maturation and inhibition of IL-12 expression." (PMID 32615983, 2020).
infection (continued). "This is consistent with the idea that latency is an unfortunate consequence of infection during a narrow window after CD4+ T cell activation." (PMID 32443452, 2020). "When analyzed in the varying E:T ratio mode or the time course of infection, the CD4-MBL-R5Nt CAR displayed consistently higher potency than the CD4-MBL CAR." (PMID 32523897, 2020). "During murine infection by L. major, increased frequencies of activated CD4+PD-1+ T effector cells were found at the infected site and in draining lymph nodes." (PMID 33193363, 2020). "We found 78% (39/50) of Envs produced high titre GFP-pseudoviruses to enable assessment of CD4+ T cell infection." (PMID 32762760, 2020). "The GALT is a major site of HIV replication and suffers a massive depletion of CD4+ T cells early in the infection." (PMID 32023301, 2020). "There was a significant reduction in the number of activated effector CD4+ T cells in mice treated post-infection with Moringa pellets." (PMID 32033605, 2020). "We have previously reported that cathepsin B suppresses infection by CD4-independent strains of HIV." (PMID 32635194, 2020). "During natural infection the HIV-1 accessory protein Nef downregulates CD4 expression on the surface of virus-infected cells." (PMID 31776278, 2020). "To date, few studies have investigated the evolution of CD4/CD8 ratios in patients initiating ART close to infection." (PMID 32258852, 2020). "Since memory T cell responses are critical to induce long-term protection against infection, the LiChimera-specific CD4+ and CD8+ T cells were also evaluated for expression of markers associated with memory cells, i.e., CD44 and CD62L." (PMID 32629975, 2020). "CD4 T cells do play an important role during the priming phase of infection in C3H/HeN mice as their depletion during vaccination with avirulent strains of T. gondii prevents development of protective CD8 T cell immunity." (PMID 32669460, 2020). "Infection related immunopathology is unlikely a consequence of hyperactivated CD4 cells present in MFYcre mice before infection." (PMID 33240286, 2020). "This leads to a differential accessibility of FabA versus FabG to gp41 epitopes exposed during binding of the HIV-1 envelope to CD4, its first receptor for infection of target cells, and thus to the recognition of distinctive regions." (PMID 33315937, 2020). "Even at the infection site, Mtb interacts with various antigen-presenting cells in order to mediate anti-Mtb immunity and coordinates the presentation of TB antigens to CD4+ and CD8+ T cell in the lymph nodes." (PMID 33101317, 2020). "There were 89% patients were categorized with Stage I or II clinical infection, and approximately 62% of patients had an average CD4 cell count of under 350/μl." (PMID 32646373, 2020). "The baseline human CD4+ T cell levels prior to infection in all mice was greater than 50% of all human CD3+ cells." (PMID 32849468, 2020). "In human infection, Th1 CD4+ T cells producing IFN-γ and TNF-α and positive delayed type hypersensitivity (DTH) responses, have been associated with the healing process." (PMID 32176691, 2020). "Following infection, we observed an early colonic Th17 response within total CD4 T cells, followed by a Th1 bias." (PMID 32457450, 2020). "By interrupting HIV pathogenesis early during infection, it is expected that existing CD4+ T cells and HSPCs as well as the host's hematopoietic capacity will be preserved for long." (PMID 32154191, 2020). "Emergence of CMV specific CD4+ T cell responses prior to the CD8+ T cell response has been shown, in a primary model of infection in solid organ transplant patients, to be associated with a lack of overt CMV disease." (PMID 32509591, 2020). "The ability of HIV to establish a reversibly silent (latent) infection in CD4+ T cells is widely regarded as the main barrier to curing HIV, but it is unclear what mechanisms govern latent HIV infection." (PMID 33253324, 2020).